RN7SKP115 (RN7SK pseudogene 115)
Gene: Miscellaneous RNA gene on chromosome 11 (100,839,630 to 100,839,946, forward strand). Ensembl gene ENSG00000200047.
Homologues: Orthologues: chimpanzee 7SK (98% identical), guinea pig 7SK (62% identical). Paralogues in human: RN7SKP124 (73% identical), RN7SKP203 (73% identical), RN7SKP255 (73% identical), 7SK (72% identical), RN7SKP250 (72% identical), RN7SKP225 (71% identical), RN7SKP90 (71% identical), RN7SKP173 (71% identical), RN7SKP180 (71% identical), RN7SKP184 (71% identical), RN7SKP224 (71% identical), RN7SKP37 (71% identical), and 284 more.